IL10 (interleukin 10)
Diseases named in the same sentence as IL10 in open-access papers (continued):
Sharing a sentence is not in itself a finding about the gene and the disease.
influenza (continued). "Importantly, these data demonstrate a direct role for EPFR-induced Tregs and IL10 in enhancing influenza morbidity and mortality." (PMID 28086957, 2017). "Lower IFNγ:IL-10 ratios and levels of the cytolytic mediator, granzyme B, in influenza-challenged peripheral blood mononuclear cells (PBMC) correlate with increased risk of influenza in vaccinated older adults." (PMID 26941738, 2016). "However, IL-10−/− mice have been found to have increased survival compared to WT mice when challenged with influenza, correlating with increased expression of Type 17 immunity associated cytokines." (PMID 25651926, 2015). "Syncytin-1 exposure leads to a marked reduction in pDC release of IFN-α/λ to influenza, but it also stimulates enhanced release of IL-10 with the potential to further impair adaptive responses as well as enhanced release of IL-6 and IL-1β both of which potentially will worsen systemic inflammation." (PMID 25831059, 2015). "Because IL-10 production was severely decreased in influenza infected IL-27Rα−/− mice compared to controls, we proposed that IL-27 induction of IL-10 might play a role in the development of secondary S. aureus pneumonia." (PMID 25651926, 2015). "Our findings demonstrate that IL-27 may partially regulate IL-17 and IL-10 production during influenza infection." (PMID 25651926, 2015). "It is important to note that IL-27 mediated IL-10 and IL-17 production may be variable throughout the time course of post-influenza S. aureus pneumonia and further study is required." (PMID 25651926, 2015). "Thus, IL-10 becomes induced in IFN-γ+CD4+ T cells during influenza by IL-27, in part mediated via STAT4." (PMID 24809349, 2014). "The role of IL-10 during acute influenza appears to be contradictory." (PMID 24846450, 2014). "Thus, a live-attenuated influenza vaccine should also allow for IL-10 expression while replicating following vaccination." (PMID 24719769, 2014). "Recent studies have suggested the source of IL-10 in the context of an influenza infection may be CD4+ and CD8+ T cells, and IL-10 expression is a high correlate to survival/protection against influenza." (PMID 24719769, 2014). "During acute influenza infection IL-10 is produced in the lungs by influenza-specific T-cells." (PMID 23478252, 2013). "However, the levels of all the cytokines and chemokines examined, with the exception of IFN-γ and IL-10 were elevated in Nox1−/y mice following influenza infection and to a greater extent (≥2–3 fold) than in WT mice." (PMID 23577160, 2013). "It is possible that prolonging antibiotic treatments beyond 72 hours could influence cytokines that increase later in the course of influenza, such as IL-10." (PMID 23478252, 2013). "Furthermore T cell responses are better correlates of vaccine protection in the elderly, with the ratio of IFNγ to the immunosuppressive cytokine IL10 better correlating with protection against influenza than serum antibody titers." (PMID 24204639, 2013). "IFN-γ and IL-10 are involved in the regulation of anti-inflammatory response to influenza." (PMID 23478252, 2013). "IL10 was also reported to play a role in immune response to influenza and herpes viruses." (PMID 22768144, 2012). "In contrast, levels of two anti-inflammatory cytokines, IL-1ra and IL-10, were elevated in influenza infection, probably to limit damages that could be provoked by an over-activated immune system." (PMID 21966414, 2011). "Similarly, virus-specific Th1 cells were shown to exert simultaneously stimulatory (IFN-γ production) and inhibitory (IL-10 secretion) functions during acute influenza infection." (PMID 19751267, 2009). "This supports the hypothesis of an early detrimental role for IL-10 during influenza infection." (PMID 40431705, 2025). "However, treated mice exhibited reduced levels of keratinocyte chemoattractant, interleukin-10 (IL-10), and systemic interferon-gamma, indicating that E. purpurea may modulate cytokines to reduce the clinical symptoms of influenza." (PMID 39452214, 2024).
influenza (continued). "Since higher levels of functional markers associated with IFN-γ expression (IL-10, CD317) are seen in BalbY with the best survival, it could be beneficial to design influenza vaccines that target a Th1 immune response, particularly in individuals who lack robust Th1 immunity." (PMID 38814732, 2024). "However, given the kinetics of the IL-10 response, which peaks at 4-weeks vaccination, this response as a correlate of protection appears to vary depending on timing of vaccination relative to the onset of the influenza season." (PMID 35128529, 2021). "In one study we showed that increasing IFNγ:IL-10 ratios at pre-and 4-weeks post-vaccination were associated with protection against A/H3N2-LCII during the 2003–2004 influenza season when there was an A/H3N2 vaccine strain mismatch and influenza began to circulate in late November." (PMID 33430191, 2021). "This dysregulation of TNF-α and IL-6 vs. IL-10 response to influenza vaccination has been linked to the downregulation of the expression of the costimulatory molecules CD80 and CD86 by activated monocytes as a predictor of the antibody response to influenza vaccination." (PMID 28769922, 2017). "Further, the IFN-γ mRNA levels were significantly higher (p < 0.05) compared to IL-4 and IL-10 mRNA levels, suggesting that Salmonella based vaccines have potential to skew the immune response toward Th1 type, which is important for the clearance of influenza infections." (PMID 28555133, 2017). "Finally, acute influenza infection was associated with low plasma concentrations of inflammatory cytokines, including IFN-γ, MIP-1β, IL-2 and IL-15, and high levels of the anti-inflammatory cytokines IL-10 and IL-1ra." (PMID 21966414, 2011). "We therefore measured the levels of several cytokines, including the pro-inflammatory TNF, IL-1β, IL-6, and IFN-γ, as well as IL-4, IL-10, IL-17A, and IL-22, in BAL samples from mice 5 days after influenza challenge." (PMID 40612502, 2025). "In influenza, MASLD patients also displayed exaggerated interferon-induced chemokine CXCL10 and immunoregulatory TGF-β1 and IL-10 responses, possibly enhancing tissue damage and impairing viral clearance." (PMID 40869413, 2025). "Twelve months after vaccination against influenza, the study participants had significantly lower IL-6 levels, and COPD patients, additionally, showed a reduction in IL-10 levels compared to baseline." (PMID 39937802, 2025). "The group of pregnant women with severe influenza (PSI) exhibited significantly increased levels of IL-4 and IL-6 compared to the PH3 group and an elevated IL-10 level compared to the CN group." (PMID 40558593, 2025). "In the Influenza infection group, the Spring PM exposure induced elevated expression of IFN-γ, IL-1β, IL-6, IL-8, TNF-α, IL-10, MCP-1, and GM-CSF relative to the control exposure." (PMID 40671793, 2025). "IL-10 is known to rise in lung tissue and BALF during influenza infection, largely from immune cells." (PMID 41502560, 2025). "In comparison to influenza and bacterial CAP, patients with AdV had higher serum IL-2, IL-1β, IL-8, IL-10, CXCL10 and MCP-1, and lower TGF-β1 concentration." (PMID 39858309, 2025). "In this study, we investigated the immunomodulatory effects of silibinin on key cytokines, IFN-γ and IL-10, in both serum and BAL fluid during influenza infection." (PMID 39850538, 2025). "When comparing major trends between cytokeratins, CK8/18 and CK19 were the most similar, including the production of the anti-inflammatory cytokines IL-2, IL-9, IL-10, and TNF-β among influenza-infected (CK+FLU+ ) populations." (PMID 39791909, 2025). "Noteworthy, syncytin-1 has been shown to weaken the antiviral response against Influenza, leading to reduced production of IFNA1, IFNL1, and IFN-γ and inducing IL10 release by peripheral monocytes (PBMCs)." (PMID 39273061, 2024).
influenza (continued). "Rapanea melanophloeos has been shown to increase IL-27 production, ultimately increasing IL-10 production, to decrease the viral titre of influenza A virus in MDCK cells, suggesting its role as an anti-influenza treatment." (PMID 38674902, 2024). "As expected, CXCL10 and IFNα levels were highest in influenza infection, whereas IL6, IL10, IL1β, and PROK2 (which is highly inducible in macrophages by LPS and other TLR2/4 agonists) reached higher levels in the bacterial infections." (PMID 39395995, 2024). "During inflammation, influenza vaccination leads to reduced levels of proinflammatory cytokine (IL-6, IL-8 and TNF-α) and an increase in IL-10 levels." (PMID 37766096, 2023). "After 14 days of LS intervention, the levels of IL-1ra, IL-6, IL-10, IL-13, Eotaxin, IFN-γ, SCF and TRAIL in serum of participants with influenza infection were significantly decreased compared with Placebo group (p < 0.05 or p < 0.01)." (PMID 36034844, 2022). "The analysis using CytoHubba, TNF, IL10, IL-6, IL-1B, JUN, and MAPK1 was found to have the highest average scores and identified as crucial targets for the anti-influenza efficacy of TFA." (PMID 35123452, 2022). "After 14 days of LS intervention, the levels of IL-1ra, Eotaxin, IFN-γ, IL-6, IL-10, IL-13, SCF and TRAIL in serum of participants with influenza infection were significantly decreased compared with Placebo group." (PMID 36034844, 2022). "In critically ill patients with influenza, disease severity is also related to elevated levels of TNF-α, IL-6, IL-8, and IL-10." (PMID 34987205, 2022). "Motivated by a reported epidemiological relationship between active tuberculosis and fatal pandemic influenza infections in South Africa, a recent study investigated the effects of IVA challenge and IL-10 signaling on bacterial load in Mtb infected mice." (PMID 33746948, 2021). "IL-10 rs1800896 C/A genotype was significantly associated with fatality in influenza A/H1N1pdm09 infections, however, in our study we could not find any association of these SNPS with influenza infection." (PMID 33766078, 2021). "CD8+ T cells produce IL-10 in response to IFNAR signaling, IL-27, and CD4+ T cell-derived IL-2 during influenza infection in mice." (PMID 32974217, 2020). "Tregs are characterized by Foxp3 expression; they dampen the immune response and limit lung injury during influenza infection through secretion of TGF-β and IL-10." (PMID 32974217, 2020). "In this setting, murine studies of influenza infection suggested that CD8+ T cells, by producing the anti-inflammatory cytokine IL-10, are important to resolve inflammation." (PMID 30881357, 2019). "A pro-inflammatory immune response to influenza and pneumococci is accompanied by the induction of IL-1, IL-6, TNF-, RANTES, MIP-1-alpha, IL-8, IL-10 and gamma interferon." (PMID 31513620, 2019). "Administration of the novel virus-like particle based vaccine elicited influenza-specific CD4+ and CD8+ T-cell responses and the induction of the cytokines IFN-γ, IL-17A, IL17F, IL-5, IL-13, IL-9, IL-10 and IL-21." (PMID 30573748, 2018). "Although BPZE1 administration resulted in a transient increase of IL-10-producing CD4+ T cells in the bronchoalveolar lavages, the role of IL-10 in BPZE1-mediated protection against influenza remains uncertain." (PMID 30581436, 2018). "CAM also improved survival in post-influenza, CAM-resistant pneumococcal pneumonia, with improved lung pathology as well as decreased interferon (IFN)-γ and increased IL-10 levels." (PMID 29621339, 2018). "Strikingly in the murine model of influenza infection, CD8+ T cells are the largest subset of the IL-10-producing LAG3+CD49b+ T cells in the lungs (86%), followed by Foxp3− CD4+ T cells, while Foxp3+ CD4+ are a minority." (PMID 30510554, 2018). "This is in apparent contrast to what was reported in the influenza model, where BPZE1 treatment resulted in reduced levels of both IL-10 and IFN-γ in the bronchoalveolar lavages after viral challenge." (PMID 30581436, 2018).
influenza (continued). "While influenza infection alone is known to induce increased expression of IL10 at the time of peak adaptive T cell response, we also observed an increase in IL10 levels in the lungs of EPFR exposed neonates at 1 dpe, prior to influenza infection." (PMID 28086957, 2017). "We were particularly interested in IL-2, IL-12p70, IFN-γ, IL-1β, IL-10, IL4, and TNF-α, given their involvement in the immune response during influenza infection and also given the phenotype of the response upon vaccination." (PMID 28792466, 2017). "Th1 cells can produce IL-10 in response to intracellular protozoan, LCMV, MCMV, or influenza infections among others." (PMID 28316998, 2017). "Specifically, monocytes (macrophage precursors) obtained from older adults prior to influenza vaccination exhibit impaired function with decreased TNF-α and IL-6 secretion, but intact IL-10 responses." (PMID 28769922, 2017). "IL-27 induces IL-10 expression by CD8+ T cells, and IL-27-dependent control of influenza-induced inflammation is partially dependent upon IL-10." (PMID 27926930, 2016). "Additionally, the induction in the gut of anti-inflammatory Il10 after influenza infection might, not only inhibit the bactericidal response of macrophages, but also cause infected macrophages to function as hosts for bacterial replication, as previously shown." (PMID 27149619, 2016). "Amongst the most significant pathways, Toll-like receptor signaling, IL-10 signaling, Role of PKR in Interferon Induction and Antiviral Response and NFkB signaling were significantly up-regulated in the influenza patients." (PMID 25365328, 2014). "More influenza NP- and PA-specific BAL CD8+ T cells were present, and higher proportions of these cells expressed intracellular IFNγ and IL-10 in PR8-infected IDO1-KO mice." (PMID 23785507, 2013). "For example, IL-10 can limit immunopathology induced by respiratory syncytial virus (RSV), and influenza, suggesting the primary function of this pathway is to limit infection-induced immune-mediated tissue damage." (PMID 23012619, 2012). "Pandemic influenza vaccines should preferentially activate both Th1 (IL-2, IFN-γ and TNF-α) and Th2 subsets (IL-4, IL-5, and IL-10) of T helper cells, since both are important for elimination of influenza virus from the host." (PMID 22069479, 2011). "Tregs limit CD8+ T cell and NK cell proliferation via IL-10 and TGF-β production while promoting Tfh cell differentiation in CD4+ T cells by sequestering IL-2, thereby enhancing germinal center B cell responses in influenza infections." (PMID 40872830, 2025). "Cytokine analysis revealed a distinct immunological pattern in pregnant women infected with influenza, characterized by the simultaneous elevation of both pro-inflammatory (IL-6, IFN-γ) and anti-inflammatory (IL-10) mediators; this finding challenges the conventional Th1/Th2 paradigm." (PMID 40558593, 2025). "Another group reports that concurrent infection with L. sigmodontis reduces the quantity and quality of antibody responses to vaccination against seasonal influenza in BALB/c and C57BL/6 mice, which is related to a systemic and sustained expansion of IL-10-producing Treg cells." (PMID 39066367, 2024). "For example, the ratio of IFN‐γ and IL‐10 secreted by immune cells collected after influenza vaccination, rather than IL‐10 levels alone, was found to be associated with protection." (PMID 37457646, 2023). "Here, we constructed influenza‐specific IgG landscapes and determined baseline concentrations of cytokines typically associated with chronic inflammation in older adults (TNF‐α, IL‐10, IL‐6, and IFN‐γ) in 30 high and 29 low influenza vaccine responders (HR and LR, respectively)." (PMID 37457646, 2023). "To further define the role of PD-1 and ICOS signaling pathways in lung tissue resident T cell expansion and IL-10 production during flu re-infection, we tested the effects of PD-1 and ICOS signaling blockades during secondary influenza infection (D respectively)." (PMID 36159872, 2022).
influenza (continued). "As previously cited in the upper airway this cytokine is associated with the reduced incidence of symptoms, and also it was reported that the lack of IL-10 compromised the development of an effective immune response during influenza infection." (PMID 33717074, 2021). "Although IL-10 is consistently upregulated in severe influenza cases in humans, the full extent of the immune regulatory role of IL-10 during influenza infection has not been explored." (PMID 33680987, 2021). "IL-10 has also been found to be 3-fold higher, and the ratio of IFNγ:IL-10 significantly lower, in elderly subjects that developed influenza compared to those that did not." (PMID 36845567, 2021). "Here the authors show that TIGIT also limits immune pathology during LCMV or influenza infections in mice by driving IL-10 expression without negatively affecting the viral load." (PMID 32152316, 2020). "They treated WT mice with recombinant IL-27 (rIL-27) following lethal dose influenza infection and found lower IL-17 levels and higher IL-10 levels correlated with increased protection without compromising viral clearance." (PMID 32974217, 2020). "Together with many other types of cytokines, levels of the interleukins, IL-8 and IL-10 are elevated over 10 times and 50 times to ~101.7 and ~ 100.8 pg/ml, respectively, in the peripheral blood in a nonfatal infection of influenza A (H5N1)." (PMID 34192260, 2020). "In the context of respiratory viral infection, T-cell-restricted deletion of IL-10 recapitulates the effects of global IL-10 blockade by augmenting Th1-dependent immunopathology during influenza and RSV infections in mice, with both CD4+ and CD8+ T cells producing IL-10 in these models." (PMID 30874596, 2019). "For IL-10, the potentiating effect was additive rather than synergistic, only observed at 4 days post-influenza infection, and reached a trend towards statistical significance." (PMID 29978355, 2018). "To complement the study of influenza-specific CMI responses stimulated by Salmonella-based influenza vaccines, we evaluated the capacity of vaccinated PBMCs to produce IFN-γ, IL-17 and IL-10 cytokines in response to the stimulation with the inactivated H7N9 recall antigen (5 μg/mL)." (PMID 29391053, 2018). "IL-10 and MIP-1β were also elevated in SCD animals after influenza infection." (PMID 28256526, 2017). "Since we had previously observed an increase in Tregs in the lungs of neonatal mice exposed to EPFRs, we hypothesized that Tregs, and their effector cytokine IL10, were critical for EPFR-induced exacerbation of influenza disease severity in neonates." (PMID 28086957, 2017). "IL-10 and TGF-β mRNA levels increased at 24 h p.i. because neuraminidase of most influenza A viruses can convert latent TGF-β to active TGF-β, which plays a pivotal role in protecting the host from influenza pathogenesis." (PMID 27525278, 2016). "In a pre-clinical model using human PBMC to test different adjuvants combined with split-virus influenza vaccines (SVV), we have shown that addition of toll-like receptor (TLR) agonists can be used to improve the IFNγ:IL-10 ratios as well as GrB responses to influenza challenge." (PMID 27322555, 2016). "In addition to mediating IL-17 and IL-10 responses, it has been reported that IL-27 signaling affects IFNγ production by CD8+ cells during primary influenza infection." (PMID 25651926, 2015). "To determine the possible impact of ST2 on pulmonary inflammation during influenza infection, we measured lung levels of cytokines (IFN-γ, TNF-α, IL-1β, IL-6, IL-10, IL-33, IL-13, IL-5) and chemokines (KC, MIP-2) at 3, 8 and 14 days following influenza inoculation." (PMID 23483993, 2013). "Unlike enhanced phagocytosis by glucocorticoid–treated human Mph, influenza-induced phagocytosis increase was independent of IL-10 or Mertk/Protein S pathway." (PMID 22238612, 2012).